ESR1 (estrogen receptor 1)
Diseases named in the same sentence as ESR1 in open-access papers (continued):
Sharing a sentence is not in itself a finding about the gene and the disease.
breast cancer (continued). "And in estrogen receptor alpha (ERα) positive breast cancer, YAP upregulates vestigial like family member 3 (VGLL3), recruiting the nuclear receptor co-repressor (NCOR2/SMRT) repressor to the estrogen receptor 1 (ESR1) super-enhancer, thereby silencing ERα transcription and inhibiting tumor growth." (PMID 40673277, 2025). "The relationship between ESR1 gene expression with IL1R1 or IL1RN genes has not been described for breast cancer." (PMID 39201290, 2024). "The finding that GEX of ESR1 and PGR can be used to predict tamoxifen benefit is clinically useful since GEX analysis is already routinely performed in patient subgroups with early breast cancer." (PMID 38587062, 2024). "Remarkably, knockdown of NPY1R significantly inhibited the growth of T47D WT cells under E2 stimulation, as well as the ligand-independent growth of ESR1 mutant cells, underscoring the essential role of NPY1R in estrogen-dependent and ESR1 mutant breast cancer cell growth." (PMID 39702552, 2024). "In addition, estrogen receptor 1 can activate SLC7A11 expression, and estrogen receptor 1 knockdown increases ferroptosis in malignant cells; also, NEDD4L ubiquitinates SLC7A11 in estrogen receptor-positive breast cancer cells during radiation." (PMID 38778030, 2024). "The biological relevance of the detected kinases is evident from their high mutation frequency in breast cancer, which is similar to other well-known non-kinase breast cancer markers such as BRCA2 and ESR1." (PMID 38784015, 2024). "MLKL mRNA expression correlated with IRF1 and STAT1 mRNA expression, but not with ESR1 expression, in breast cancer cell lines." (PMID 38474369, 2024). "Moreover, we observed a significant negative correlation between POU4F1 expression and master transcription factors of ER positive breast cancer, such as ESR1, FOXA1 and GATA3, in breast cancer patients from the TCGA and METABRIC cohorts." (PMID 38491910, 2024). "The expression levels of the GADD45A and ESR1 genes were compared across breast cancer and adjacent non-tumor tissues sourced from patient samples, utilizing curated data from the GEPIA database." (PMID 38732206, 2024). "Patients in stages 3 and 4 of breast cancer subtypes such as Her2, Luminal A, and Luminal B who test positive for CCND1, CTSD, EGFR, BCL2, and ESR1 gene expression might benefit in this regard." (PMID 39202273, 2024). "The analysis revealed a significant upregulation of ESR1 expression in breast cancer tissues compared to their non-tumoral counterparts, whereas GADD45A exhibited a contrasting downregulation in tumoral tissues." (PMID 38732206, 2024). "Previous studies have demonstrated that the mRNA and protein expression levels of PD-L1 are significantly elevated in ERα-positive breast cancer cell lines and that ESR1 is negatively correlated with PD-L1 mRNA expression." (PMID 39544302, 2024). "In addition, we demonstrated that combined ESR1 expression and EERES is a good predictor for better survival for hormonal therapy-treated breast cancer patients." (PMID 38582811, 2024). "It inhibits cell proliferation in wild-type ERα and ESR1 mutant breast cancer cell lines." (PMID 39767607, 2024). "Despite this, profiling of protein abundance and phosphorylation levels have not been explored in ESR1 mutant breast cancers." (PMID 38519482, 2024). "Tumor cells found in breast cancer expressing high KRT7 and low ESR1 phenotypes may experience increased plasticity and heterogeneity." (PMID 38892065, 2024). "A significant (p < 0.05) positive correlation was also observed between ESR1 and IRF6 gene expression levels in Basal and Luminal A breast cancer patients, and there was also a significant (p < 0.05) positive correlation between ESR1 and NFIL3 gene expression levels in Basal breast cancer patients." (PMID 39765744, 2024). "In MCF-7 breast cancer cells, acetylated H3K27 promotes the transcription of ESR1." (PMID 39684286, 2024).
breast cancer (continued). "Additionally, the mRNA expression of both estrogen receptor alpha (ESR1) and beta (ESR2) was analyzed to further understand the differential response of luminal breast cancer cell lines with distinct basal levels of ESR2 expression." (PMID 39767718, 2024). "The analysis of clinical data indicated that the correlation between the expressions of ADAM12 and ESR1 in patients with Luminal A and Luminal B breast cancer was negative; however, the expressions of ADAM12 and ESR2 were not statistically significant." (PMID 39596804, 2024). "In patients with Basal or Her2 breast cancer, no substantial connection was identified between the ESR1 and CTSD gene expression." (PMID 39202273, 2024). "As a reminder, the decrease in SFRP1 expression in non-tumoral (MCF10A) and pre-tumoral (MCF10AT1) breast lesions was inversely correlated with ESR1 expression, highlighting the existence of a differential role of SFRP1 with regards to breast cancer stage and molecular subtype." (PMID 37190179, 2023). "Thereafter, we compared the correlation between SFRP1 and biomarkers of breast cancer molecular subtyping, such as ESR1, PGR, and HER2 in both breast non-tumoral and tumoral tissues." (PMID 37190179, 2023). "This cohort contained a subset of genes that could be considered potential biomarkers for breast cancer progression, including FOXA1, MLPH, ESR1, AR, GATA3, TFF1, THSD4, and TBC1D9." (PMID 38020889, 2023). "For example, both tumors were mainly composed of epithelial breast cancer cells (EPCAM+) with a similar distribution of hormone receptors (ERBB2 for HER2, ESR1 for estrogen receptor, and PGR for progesterone receptor) and histology markers (CDH1 for E-cadherin)." (PMID 37301892, 2023). "Moreover, the overexpression of DSCAM-AS1 in tamoxifen-resistant cell line models, which also overexpress ESR1, highlights the potential role of DSCAM-AS1 in endocrine therapy resistance in breast cancer." (PMID 37395734, 2023). "Finally, intersecting specific DMGs of the two patients, we observed common tumor pathways involved in lymphoma and breast cancer including transcription factors and oncogenes (e.g., FOXD3/ESR1/HOXA9/BCL11B)." (PMID 37029309, 2023). "Additionally, a significant positive correlation was observed between ESR1 and HOTAIR expression levels in breast cancer patients." (PMID 38114755, 2023). "Furthermore, mRNA expression analysis of three breast cancer markers (HER2, PGR, and ESR1) revealed relatively high expression in VCL006, VCL008, and VCL012 compared to other cell lines." (PMID 38033642, 2023). "This study aims to quantify the expression levels of the ESR1, HOTAIR, and miR-130a genes in serum samples obtained from Egyptian female breast cancer patients and examine the correlations between their expression levels and the clinicopathological features of the disease." (PMID 38114755, 2023). "This study aimed to elucidate the gene expression profile of Estrogen Receptor-1 (ESR-1), long non-coding RNA HOTAIR, and microRNA-130a in the serum of Egyptian breast cancer patients, evaluating the potential of HOTAIR and miR-130a as biomarkers for predicting pathological parameters in BC." (PMID 38114755, 2023). "Positive correlations between ARID1A and PGR expression, and negative correlations between EZH2 and PGR/ESR1 expression, were also observed in breast cancer patient samples." (PMID 35326450, 2022). "Yet, the association of intramammary levels of E2 and E1 with the signaling leading to ESR1-dependent proliferation in human breast tissues in women without breast cancer is hitherto unexplored." (PMID 34921608, 2022). "Taken together, these results validate the association between DSCAM-AS1 and miR-130a to maintain ESR1 levels in PR-positive breast cancer cells with a consistent inverse correlation of miR-130a with the expression of DSCAM-AS1 and ESR1 in the TCGA patient samples." (PMID 36578092, 2022).
breast cancer (continued). "The expression of key markers associated with proliferation (MKI67, PCNA, CCNB1, MYBL2, BUB1, CCND1), apoptosis (BCL2, CASP7, CASP8, CASP9, CASP3, BAX, APAF1), differentiation (CDH1, CD24, EPCAM, ESR1, NGFR, RUNX1), and breast cancer stemness (CD44, ITGA6, DNER, ALDH1A3, ABCG2, PROCR) was assessed." (PMID 35183258, 2022). "Although our study identified possible pathological roles for IGF1, ESR1, and CXCL12 in breast cancer and a potential synergistic effect of formononetin with immune checkpoint inhibitors in breast cancer immunotherapy, the limitation of this study is that it is only a data analysis-based prediction." (PMID 35463082, 2022). "Interestingly, the expression of ESR1 in IBT was significantly downregulated, which was consistent with the expression changes of Her2+ breast cancer and TNBC samples." (PMID 35992864, 2022). "In both cases, broadlyaccepted breast cancer drivers such as BRCA1 and ESR1 are central nodes in the network.The network analysis has revealed severalinfluential DCDs that are not curated CGC genes yet, for example E2F2 and THRA fromsingle-cell, and SIN3A from bulk data." (PMID 36124841, 2022). "EN1 is highly expressed in breast cancer (BRAC), and ESR1 can increase eRNA transcription in BRAC." (PMID 36217201, 2022). "Based on our results obtained using GEO disease data and molecular docking analysis, we suggest that the intervention of formononetin in breast cancer may be achieved by regulating IGF1, ESR1, and CXCL12." (PMID 35463082, 2022). "Importantly, in ER+ breast cancer miR‐221/222 targets ESR1/ERα and can thereby confer resistance to estrogen/ERα‐targeted therapies." (PMID 35656866, 2022). "In addition, ESR1 expression significantly decreased after TSTD1 knockdown and significantly increased after transfection of TSTD1 in separate breast cancer cell lines." (PMID 36419875, 2022). "In addition, in ER+ breast cancer, TRIM3 promotes SUMO modification of estrogen receptor 1(ESR1) and activated the ER signaling pathway." (PMID 36261847, 2022). "In addition to regulating ESR1 gene expression, FOXA1 acts as a pioneer factor for AR expression not only in prostate but also in breast cancer, and, TNBCs that lose metastatic potential co-express FOXA1 and AR." (PMID 36171192, 2022). "Additionally, the expression pattern of miR-130a was found to be inversely correlated with that of ESR1 and DSCAM-AS1 in cell lines and patients with breast cancer." (PMID 36578092, 2022). "In conclusion, our findings predict that IGF1, ESR1, and CXCL12 may be effective targets of formononetin as a therapeutic for breast cancer." (PMID 35463082, 2022). "While BNAT1 is located on chromosome 21, questions may arise as to whether other ESR1-modulating factors on different chromosomes including TMPO-AS1 and Eleanors contribute to the expression of BNAT1 in breast cancer cells." (PMID 36429038, 2022). "Accordingly, ESR1 is highly expressed in luminal breast cancer and lowly expressed in non-luminal breast cancer." (PMID 34249704, 2021). "In human breast cancer, the most aggressive tumors do not show the presence of the ERα, which has been attributed to methylation of the CpG island in the promoter of the ESR1 gene." (PMID 33652604, 2021). "Mammary tumors in K5-ERAS mice express the estrogen receptor ESR1 but do not seem to be dependent on hormonal signaling, as transgenic females with several pregnancies develop mammary tumors with a prevalence similar to that of virgin females." (PMID 34771750, 2021). "It has been reported that the TF network composed of estrogen receptor alpha (ESR1), FOXA1, and GATA3 may control the gene expression pattern in luminal breast cancer." (PMID 34249704, 2021). "For the first time, we elucidated that ESR1 and NEDD4L functioned together after radiation treatment and finally induced ferroptosis in breast cancer cells, which provides novel insight into the guidance of clinical treatment of breast cancer." (PMID 35252218, 2021).
breast cancer (continued). "Triple-negative breast cancer (TNBC) is a breast cancer in which estrogen receptor 1 (ESR1), progesterone receptor (PR), and human epidermal growth factor receptor 2 (HER-2) are all negative." (PMID 34768896, 2021). "Several targets belong to the estrogen receptor, such as ESR1 (estrogen receptor-α, degree = 5), ESR2 (estrogen receptor-β, degree = 5), and PGR (progesterone receptor, degree = 6), are major therapeutic targets of breast cancer." (PMID 34083561, 2021). "In addition, four genes CCND1, ESR1, STAT3, and NCOA1 were enriched for mammary neoplasms, experimental (C0024668)." (PMID 34504716, 2021). "This has been acknowledged by pathologists in the breast cancer field, but there is currently no motivation to exchange ER-IHC assays in high-resource settings for ESR1 mRNA." (PMID 34050358, 2021). "However, the enrichment for ESR1, FOXA1, and GATA3 was stronger for ER-positive CCVs than for ER-negative or overall breast cancer CCVs." (PMID 34439109, 2021). "It was reported that OCT1 binds to the promoter region of ESR1 and up-regulates ERα in breast cancer cells, which implies that some of the OCT1 induced genes may be dependent on ERα expression." (PMID 34768935, 2021). "We analyzed 3217 population-based invasive primary (nonmetastatic) breast cancers (within the SCAN-B study, ClinicalTrials.gov NCT02306096), sampled from initial diagnosis prior to any treatment, for the presence of ESR1 mutations using RNA sequencing." (PMID 33937624, 2021). "While the detailed mechanisms of the potential interactions between ESR1+ cells and ESR1– cells are yet to be better defined, this finding offers an important explanation as to why most of the estrogen-responsive breast cancers are not homogeneously 100% ER+." (PMID 34944995, 2021). "RNA levels of both factors are much lower than those of FOXA1 in breast cancer, and neither are positively correlated with ESR1 expression." (PMID 34831189, 2021). "Accordingly, the estrogen receptor alpha coding gene ESR1 is upregulated in luminal breast cancer and downregulated in non-luminal breast cancer." (PMID 34249704, 2021). "This subset had reduced expression for genes involved in immune response and reduced accessibility at regions proximal to metabolism genes, despite no measurable difference in expression for typical breast cancer markers, such as PR, ESR1, and ERBB2." (PMID 34922480, 2021). "ESR1, FOXA1, GATA3, and EP300 TFBSs were enriched in CCVs for overall breast cancer." (PMID 34439109, 2021). "In breast cancer we reported that ESR1 methylation in CTCs and ctDNA was correlated with lack of response to treatment." (PMID 34572834, 2021). "We also tested whether SNAPD could distinguish different cell types from the same tissue of origin by evaluating estrogen receptor (ESR1) expression in SK-BR-3 and MCF7 breast cancer lines." (PMID 34233007, 2021). "Three genes CCND1, ESR1, and STAT3 were enriched for mammary neoplasms, experimental (C0024668)." (PMID 34504716, 2021). "Consistently, an immune genetic profiling study found a negative correlation between TILs and ESR1/ESR2 expression ratio in luminal breast cancer." (PMID 35008370, 2021). "In addition, resistance of ESR1-MUT to tamoxifen and fulvestrant is far less prominent in HEK-293T cells compared to breast cancer cell lines, and ESR1-WT expression alongside ESR1-MUT reduces resistance." (PMID 34392831, 2021). "Moreover, we reported that in breast cancer, CST6 and BRMS1 methylation was detected in ctDNA and CTCs, in ovarian cancer RASSFIA and ESR1 methylation was detected in ctDNA, while in NSCLC BRMS1 and SOX17 methylation was detected in ctDNA." (PMID 34572834, 2021).
breast cancer (continued). "Reducing the coverage to as low as to 100,000 mapped reads was enough for reliable estimation of HER2 and ESR1 levels in breast cancer tissues, while not less than a million mapped reads was required for PGR." (PMID 32397474, 2020). "The results showed that potential active ingredients of Poria cocos might interfere with breast cancer through synergistic regulation of PTGS2, ESR1, and FOS." (PMID 33149754, 2020). "Evaluating the same assay on non-TNBC revealed four genes: ERBB2, ESR1, PHGDH, and TYMS containing both germline and somatic mutations significantly associated with that type of breast cancer." (PMID 32724790, 2020). "Notably, ESR1 and XBP1 are co-expressed in breast cancer tissues, and XBP1s can bind to the X-box in the ESR1 promoter, thus inducing its transcription." (PMID 33291081, 2020). "Potential active ingredients of Poria cocos may interfere with breast cancer through synergistic regulation of key genes (PTGS2, ESR1, and FOS) that participate in the PPAR signaling pathway." (PMID 33149754, 2020). "The breast cancer cell lines MCF7 and T47D are very sensitive to a selection of antihormonal drugs, which prompted us to investigate whether ESR1, PGR, and GREB1 protein show similar abundance profiles across the NCI60 panel as their p-sites." (PMID 32686665, 2020). "Examination of miR‐18a expression in a set of human ER+ breast cancer specimens showed a negative correlation between miR‐18a and ESR1 transcripts as well as ER protein." (PMID 32543775, 2020). "The first two exons of ESR1 were found to fuse with an N-terminal truncated CCDC170 fragment (ΔCCDC170); the fusion gene was enriched in endocrine resistant luminal B breast cancers and its expression was driven by the ESR1 promoter." (PMID 31336602, 2019). "In patients diagnosed with stage III breast cancer, 45% of biopsies (5 patients per group) were negative for ESR1 expression." (PMID 31319484, 2019). "An example concerns estrogen receptor 1 (ESR1) gene hypermethylation, which may be involved in the development of breast cancer." (PMID 31555578, 2019). "The results indicated that ESR1, PGR, EGFR, PTGS2, and Src may be the potential therapeutic target of RYNXC for the treatment of breast cancer." (PMID 30906412, 2019). "Breast cancers are often classified by the presence or absence of three receptors: estrogen receptor (ESR1), progesterone receptor (PGR), and the HER2 epidermal growth factor receptor (ERBB2)." (PMID 31684899, 2019). "Although some genetic variations in canine ESR1 gene were reported, their influence in clinicopathological features and progression of canine mammary tumors has not been fully evaluated." (PMID 31506083, 2019). "To date, and to the best of the author’s knowledge, the influence of ESR1 genetic profile in clinicopathological features and progression of canine mammary tumors has not been fully assessed." (PMID 31506083, 2019). "In line with that, other breast cancer assays, like the GeneXpert Breast Cancer STRAT4 assay from Cepheid, that also measures the expression levels of ERBB2, ESR1, PGR and MKI67, found that macrodissection of whole tissue sections is not required for accurate assessment of these genes by RT-qPCR." (PMID 30342538, 2018). "Several genes that correlate with ESR1 in breast cancer do not show a similar correlation in ovarian cancer, and in breast cancer, GREB1 and other E2-regulated genes correlated with serum E2 changes throughout the menstrual cycle." (PMID 29973689, 2018). "miR-22 is a classical example of the negative correlation between ESR1-targeting miRNA expression and ER status in breast cancer." (PMID 30214383, 2018). "By a comparison of RNA-seq data in primary breast cancers, we show that both RET and GFRA1 correlate with expression of ESR1, suggesting that they may be targets of ERα signaling in primary tumors." (PMID 29608602, 2018).